COL11A1 (collagen type XI alpha 1 chain)
Diseases named in the same sentence as COL11A1 in open-access papers (continued):
Sharing a sentence is not in itself a finding about the gene and the disease.
pancreatic cancer (23 papers, 2013 to 2025). "COL11A1 was found to be a prognostic factor in OSCC that promoted the conversion of cancer-associated fibroblasts during pancreatic cancer progression and seemed to promote the migration and invasion of lung adenocarcinoma cells." (PMID 39769183, 2024). "COL11A1 has been reported markedly associated with head and neck, oral cavity/pharynx, breast, oesophagus, lung, colon, stomach, ovary, and pancreas cancers." (PMID 37238942, 2023). "To examine the underlying mechanism by which COL11A1 promotes the invasion and migration of pancreatic cancer cells, we measured the expression levels of EMT markers and MMP-2/9 using Western blotting and immunofluorescence." (PMID 35327583, 2022). "Our previous studies also confirmed that COL11A1 is highly expressed in pancreatic cancer cells and associated with apoptosis and gemcitabine resistance." (PMID 35327583, 2022). "GEM decreased Akt activity, causing mitochondrial apoptosis in pancreatic cancer cells; however, COL11A1 impaired this effect." (PMID 33531986, 2021). "Subsequently, we used a pancreatic cancer tissue microarray (n = 95) for determining the association of COL11A1 expression with clinicopathological characteristics." (PMID 34183642, 2021). "Among them, the COL11A1 gene is overexpressed in pancreatic cancer and the protein encoded by the COL11A1 gene may be involved in fibrous proliferative events in pancreatic cancer." (PMID 34461940, 2021). "Furthermore, AktSer473 and CREBSer133 play a vital role in controlling the ECM-associated proliferation of pancreatic cancer cells under direct regulation of COL11A1." (PMID 33531986, 2021). "In pancreatic cancer, COL11A1 modulates apoptotic inhibition and chemoresistance by activating the Akt/CREB/BCL-2/BAX signaling pathway." (PMID 40927672, 2025). "Other studies have also recorded COL11A1 overexpression in CAFs of pancreatic cancer and suggested that it is a CAF-specific marker." (PMID 35847935, 2022). "As reported in different studies, pancreatic cancer cells expressed a high level of COL11A1, and this high expression has a good value as a biomarker of activated CAFs and PAAD cancer." (PMID 36415513, 2022). "Previous studies have shown that both Snail and E-cad are related to cell stemness, and our research further confirmed that COL11A1 affects the expression levels of Snail and E-cad in pancreatic cancer cells." (PMID 35327583, 2022). "All data indicate that COL11A1 contributes to the invasion and migration abilities of pancreatic cancer cells." (PMID 35327583, 2022). "Transwell assay results illustrated that high COL11A1 expression markedly enhanced the invasion and migration of pancreatic cancer cells." (PMID 35327583, 2022). "In this study, we investigated the influence of COL11A1 on the invasion and migration abilities of pancreatic cancer cells and explored its potential molecular mechanisms." (PMID 35327583, 2022). "In the current study, we showed that COL11A1 enhanced the invasion and migration of pancreatic cancer cells and promoted the EMT process and cell stemness." (PMID 35327583, 2022). "In the current study, we assessed mRNA expression of COL11A1 and its receptors and created a testing-model of both a COL11A1-overexpressing tumor microenvironment and/or altered-COL11A1 expression in pancreatic cancer cell lines." (PMID 33531986, 2021). "In the current work, we further revealed that COL11A1 inhibits apoptosis in pancreatic cancer cells by activating Akt/CREB/BCL-2 signaling." (PMID 33531986, 2021). "In this study, COL11A1 increases BCL-2 expression while decreasing BAX expression through activation of Akt/CREB signaling in BxPC-3 human pancreatic cancer cell line." (PMID 33668097, 2021). "We propose that COL11A1/Akt represents a novel target for therapeutic development in pancreatic cancer." (PMID 33531986, 2021).
pancreatic cancer (continued). "Next, we observed that AktSer473/CREBSer133 activation by COL11A1 modulates the coordinated functions of BAX/BCL-2 in decreasing the apoptotic program in pancreatic cancer cells." (PMID 33531986, 2021). "Results revealed that COL11A1-coated increased both the expression level of s-COL11A1 and L-COL11A1 in pancreatic cancer cells, and siCOL11A1 markedly reduced expression of COL11A1 in cancer cells." (PMID 33531986, 2021). "In this study, we suggest that COL11A1/Akt modulates apoptotic inhibition and induces chemoresistance in pancreatic cancer cells." (PMID 33531986, 2021). "In conclusion, COL11A1 modulates apoptotic inhibition and chemoresistance in pancreatic cancer cells by activating the Akt/CREB/BCL-2/BAX signaling pathway." (PMID 33531986, 2021). "Another study in a mouse model of pancreatic cancer suggests that COL11A1 can be activated by the Hedgehog signaling pathway." (PMID 33668097, 2021). "And, the expression level of s-COL11A1 was tested by ELISA in the four pancreatic cancer cells (BxPC-3, Capan-1, Mia PaCa-2, PANC-1) treated with coating-COL11A1 for 48 h." (PMID 33531986, 2021). "We demonstrated that COL11A1 activates Akt signaling to enhance the proliferation of pancreatic cancer cells and their ability to evade apoptosis." (PMID 33531986, 2021). "We found that integrin α1β1 and DDR2 mediate COL11A1-induced p-Akts437 activation during pancreatic cancer development, suggesting that blocking integrin α1β1 or DDR2 to inhibit the functions of COL11A1 is specific but not exclusive." (PMID 33531986, 2021). "In conclusion, COL11A1 mediates apoptosis inhibition and chemoresistance in pancreatic cancer cells by activating the Akt/CREB/BCL-2/BAX signaling pathway." (PMID 33531986, 2021). "Genes (n = 10) in cluster 2 were entirely labeled as activated stroma, containing periostin (POSTN), fibronectin 1 (FN1) and collagens (COL10A1, COL11A1), which have already been identified as deregulated in precursor lesions of pancreatic cancer." (PMID 29675033, 2018). "We have applied the antibody against human pro-COL11A1 to breast, colon, neck and head tumors (papers in preparation), and the outcome is very similar to pancreatic cancer: it almost exclusively stains CAFs." (PMID 24194920, 2013). "The downregulation of COL11A1 in in vitro co-cultures of pancreatic cancer and stromal cells has been reported." (PMID 24194920, 2013). "In addition, COL11A1 mediates mitochondrial apoptotic evasion to enhance chemotherapy tolerance in pancreatic cancer cells." (PMID 38572434, 2024). "Interestingly, stage IIB resulted in an increased expression of genes encoding constituents of collagen X (COL10A1), collagen X1 (COL11A1), and collagen XII (COL12A1) isoforms, which have been reported to be prognostic markers of pancreatic cancer metastasis." (PMID 35565326, 2022). "Recent studies have found that COL11A1 plays an important role in the occurrence and development of tumors, and its expression is upregulated in head and neck squamous cell carcinoma and in ovarian, gastric, and pancreatic cancer." (PMID 35149954, 2022). "In addition, we performed a colony formation assay to evaluate the effect of COL11A1 on the stemness of pancreatic cancer cells." (PMID 35327583, 2022). "To further verify that COL11A1 promoted the EMT process in pancreatic cancer cells by activating the AKT/GSK-3β/Snail signaling pathway, we first detected the expression levels of E-cad, N-cad, VIM, and MMP-2/9 in PANC-1 cells with different treatments by Western blotting." (PMID 35327583, 2022). "In pancreatic cancer cells, the COL11A1/Akt axis disrupts the balance between BAX and BCL-2, and inhibits the release of cytochrome C, thereby destroying mitochondrial function and promoting apoptosis escape in turn leading to drug resistance in these cancer cells." (PMID 35847935, 2022). "Therefore, COL11A1 enhances the stemness of pancreatic cancer cells by activating the AKT/GSK-3β/Snail signaling pathway." (PMID 35327583, 2022).
pancreatic cancer (continued). "Our previous study demonstrated that COL11A1 can phosphorylate AKT in pancreatic cancer cells." (PMID 35327583, 2022). "Thus, the present findings indicate that BAX acts as a fundamental promoter of the molecular cascade by which COL11A1 mediates antiapoptotic events in pancreatic cancer cells." (PMID 33531986, 2021). "In addition to mediating cell adhesion to COL11A1, we and others have shown that COL11A1 promotes ovarian and pancreatic cancer cell survival and chemotherapy resistance through ITGα1β1 and DDR2 in vitro." (PMID 33668097, 2021). "Moreover, we identified that COL11A1/Akt signaling decreased the proapoptotic activity of GEM in pancreatic cancer cells, which, in turn, attenuated its anticancer properties." (PMID 33531986, 2021). "In addition, s-COL11A1 and the levels of COL11A1 in pancreatic cancer total cell lysate (L-COL11A1) in four pancreatic cancer cell lines was detected after stimulation with different conditions by western blotting." (PMID 33531986, 2021). "Furthermore, in breast, colorectal, and pancreatic cancer, there is a progressive increase in the expression of the COL11A1-matrisome signature during tumor development from normal to adenoma to carcinoma in-situ, and further to invasive carcinoma." (PMID 33668097, 2021). "To further study the mechanism by which COL11A1 affects proliferation and apoptosis in pancreatic cancer cells, we investigated the effect of COL11A1 treatment through coated cell culture plates on activation of the Akt, Jnk and Erk1/2 molecules in BxPC-3 cells." (PMID 33531986, 2021). "However, after COL11A1 was knocked down in pancreatic cancer cells by siRNA, cell proliferation and GEM resistance were decreased." (PMID 33531986, 2021). "In addition, COL11A1 was also observed to over-express in ovarian and pancreatic cancer and to be an indicator of poor clinical outcome of cancer treatment." (PMID 30390627, 2018). "Pancreatic cancer cells express high levels of COL11A1 mRNA, as shown by quantitative RT-PCR." (PMID 24194920, 2013). "The expression of COL11A1 protein could be involved in desmoplastic events in pancreatic cancer, but an antibody that specifically stains the COL11A1 protein is not currently available." (PMID 24194920, 2013). "The collagen11A1 (COL11A1) gene is overexpressed in pancreatic cancer." (PMID 24194920, 2013). "Therefore, we propose that COL11A1 inhibitors have high therapeutic potential in simultaneously affecting EMT/CSC properties in pancreatic cancer, thereby suppressing the migration and invasion of cells, which provides an additional means for implementing conventional therapy." (PMID 35327583, 2022). "The expression of five key genes (MMP11, COL10A1, SERPINE1, COL11A1, and EPYC) in normal pancreatic and pancreatic cancer cell lines were detected using qPCR." (PMID 38572434, 2024). "In the present study, we elucidated the function of COL11A1 in promoting EMT and cell stemness via the AKT/GSK-3β/Snail signaling pathway, which facilitates the invasion and migration of pancreatic cancer cells." (PMID 35327583, 2022). "Conversely, after COL11A1 was silenced in BxPC-3, Capan-2, and PANC-1 cells using siCOL11A1, the invasion and migration abilities of the pancreatic cancer cells were significantly suppressed." (PMID 35327583, 2022). "However, the function of COL11A1 in the development of pancreatic cancer cells remains unclear." (PMID 33531986, 2021). "Muscle, intestine and stomach expression 1 (Mist1), a transcriptional repressor can inhibit COL11A1 expression and reverse EMT in a pancreatic cancer mouse model." (PMID 33668097, 2021). "We assessed mRNA levels of COL11A1 and its receptors (integrin α1β1 and DDR2) by RT-qPCR in the pancreatic cancer cell lines BxPC-3, Capan-1, Mia PaCa-2 and PANC-1." (PMID 33531986, 2021). "Next, we investigated the mechanism by which COL11A1 affects growth, gemcitabine (GEM) resistance and apoptosis in pancreatic cancer cells." (PMID 33531986, 2021).
pancreatic cancer (continued). "Results of bioinformatic analysis and IHC analysis suggested that COL11A1, GJB2 and CTRL are novel predictive biomarkers for pancreatic cancer." (PMID 30410422, 2018). "The result showed that high expression level of COL11A1, GJB2 or low expression level of CTRL in pancreatic cancer tissue sections indicated poorer prognosis and less survival rate." (PMID 30410422, 2018). "We validated the expression level of COL11A1, GJB2 and CTRL with IHC assay of 46 paired pancreatic cancer and para-cancerous tissue sections." (PMID 30410422, 2018). "In summary, our study demonstrated that COL11A1 effectively induced EMT progression and cell stemness by activating the AKT/GSK-3β/Snail signaling pathway to enhance the migration and invasion abilities of pancreatic cancer cells." (PMID 35327583, 2022). "Additionally, our data showed that COL11A1/Akt/CREB altered the balance between BCL-2 and BAX and mediated their mitochondrial translocation in pancreatic cancer cells." (PMID 33531986, 2021). "COL11A1/Akt disturbed the BCL-2/BAX balance, inhibiting cytochrome c (Cyt-C) release and binding of Apaf-1/procaspase-9/Cyt-C, which suppressed the apoptotic program and induced GEM resistance in pancreatic cancer cells." (PMID 33531986, 2021). "To further confirm this, we detected the expression level of s-COL11A1 in supernatant medium and L-COL11A1 in total cell lysate of the four pancreatic cancer cells (BxPC-3, Capan-1, Mia PaCa-2, PANC-1) treated with COL11A1 protein for 0h, 12h, 24h, 48h by western blotting." (PMID 33531986, 2021). "For example, although studies in pancreatic cancer have highlighted the role of COL11A1 as a cancer-specific but not inflammation-specific biomarker, COL11A1 overexpression has been identified in chronic inflammatory diseases like osteoarthritis." (PMID 33668097, 2021). "COL11A1, GJB2 and CTRL are novel predictive biomarkers for pancreatic cancer." (PMID 30410422, 2018). "Furthermore, no published paper evaluated the expression and predictive value of COL11A1, GJB2 and CTRL in pancreatic cancer." (PMID 30410422, 2018). "Finally, we selected and validated the clinical predictive value of COL11A1 (collagen alpha-1(XI) chain), GJB2 (gap junction beta-2 protein) and CTRL (chymotrypsin-like protease CTRL-1) with immunohistochemical (IHC) analysis of 46 paired pancreatic cancer and para-cancerous tissue sections." (PMID 30410422, 2018).
Marshall syndrome (22 papers, 2012 to 2025). "Pathologically, a variety of developmental malformations and structural abnormalities of organs are caused by loss of COL11A1, including type II Stickler syndrome and Marshall syndrome." (PMID 36160004, 2022). "Different COL11A1 gene variants are associated with type II Stickler and Marshall syndromes which are congenital conditions that include high myopia and blindness from retinal detachment." (PMID 36036827, 2022). "COl11A1 is associated with Marshall syndrome and Stickler syndrome type II or autosomal dominant deafness type 37." (PMID 34440452, 2021). "Marshall syndrome is caused by an autosomal dominant mutation in COL11A1 and shares many features with Stickler syndrome." (PMID 31415586, 2019). "Pathogenic mutations in this gene can result in type II Stickler syndrome and Marshall syndrome, while rs1676486 on COL11A1 is associated with lumbar disc herniation susceptibility." (PMID 30809385, 2019). "The human orthologs of col11a1 and col2a1a are associated with Stickler and Marshall syndromes, which cause visual dysfunction." (PMID 23300608, 2012). "The girl (P.22) with the COL11A1 mutation had a phenotype consistent with mild Marshall syndrome (MIM #154780), with midfacial hypoplasia, cleft palate, a less severe ocular presentation, but striking ocular hypertelorism, and short stature with spondyloepiphyseal dysplasia." (PMID 35250876, 2022). "However, COL11A1 is associated with type II Stickler and Marshall syndromes, which are congenital conditions that include high myopia and blindness due to retinal detachment." (PMID 30809385, 2019). "Most patients with Marshall syndrome have a splice-site mutation in the COL11A1 gene." (PMID 28841907, 2017). "Pathogenic monoallelic variants in the COL11A1 gene are primarily linked to autosomal dominant Stickler syndrome type II (STL2) MIM #604841, Marshall syndrome (MRSHS) MIM #154780, and non-syndromic hearing loss (ADNSHL) at the DFNA37 locus MIM #618533." (PMID 38674395, 2024). "At that time, we suspected Marshall syndrome, but no mutation was identified in exons or exon/intron boundaries of the COL11A1 gene." (PMID 28841907, 2017).
lung cancer (21 papers, 2012 to 2025). A malignant neoplasm involving the lung. "Mutation in COL11A1 has been reported in up to 75% of cSCC, and is associated with higher genome mutation density in lung cancer, suggesting a role for genome destabilization." (PMID 29141020, 2017). "COL11A1 upregulation in tumor tissue versus normal tissue has been demonstrated in gastric cancer, non-small cell lung cancer, pancreatic cancer and this expression has been associated with metastasis in oral cavity and oropharynx, ovarian and lung cancer." (PMID 26466668, 2015). "Also it would be useful to evaluate the expression of COL11A1 variants in other cancers such as oropharynx, ovarian and lung cancer, wherein the expression of COL11A1 has been shown to be associated with disease progression." (PMID 26466668, 2015). "Overexpression of COL11A1, Hedgehog target gene, is associated with poor prognosis in lung cancer." (PMID 22912720, 2012). "Collagen type XI α1 (COL11A1), a minor fibrillar collagen, which plays a crucial role in cell proliferation, migration, and tumorigenesis of many malignancies, may be a valuable diagnostic marker for lung cancer." (PMID 36091765, 2022). "In lung cancer, mir-144–3p can inhibit the proliferation, invasion and migration of lung adenocarcinoma by targeting COL11A1 to down-regulate its expression level." (PMID 36160004, 2022). "RCN1 and COL11A1 are highly expressed in lung cancer and promote lung cancer cell proliferation, migration, and invasion." (PMID 35978854, 2022). "In lung cancer cell lines, elevated COL11A1 expression also mediates resistance of cancer cells to cisplatin." (PMID 35847935, 2022). "In lung cancer specimens it has been observed that COL11A1 expression is increased in recurrent tumors." (PMID 33668097, 2021). "In lung cancer cell lines, elevated COL11A1 expression also mediates resistance of cancer cells to cisplatin, a commonly used chemotherapy drug." (PMID 33668097, 2021). "Plasma samples from lung cancer patients and healthy heavy-smokers controls were tested for levels of COL11A1 and COL10A1 (n = 57 each) and SPARC (n = 90 each)." (PMID 30227835, 2018). "The amount of plasma COL11A1 can aid with lung cancer diagnosis and prognosis." (PMID 37476379, 2023). "Besides, upregulated ANGPT1 and downregulated COl11A1 are related to a better prognosis in lung cancer metastasis and proliferation in colorectal cancer." (PMID 32093414, 2020). "Collectively, AHNAK, COL11A1, and COL6A3 may be potential candidates for therapeutic and diagnostic biomarkers in head and neck cancer and lung carcinoma." (PMID 26352260, 2015). "To demonstrate the potential clinical utility of ECM-related proteins as lung cancer circulating biomarkers, we analyzed by ELISA assay matched plasma samples from 57 patients (TU) and 57 controls (CTR) for COL11A1 and COL10A1 and from 90 patients (TU) and 90 controls (CTR) for SPARC." (PMID 30227835, 2018). "The aim of the present study was to measure the levels of three circulating ECM related proteins (COL11A1, COL10A1 and SPARC) in plasma samples of lung cancer patients and in healthy heavy-smokers controls and test whether such measurements have diagnostic or prognostic value." (PMID 30227835, 2018). "Thus, further studies are needed to investigate whether B-Myb activates ERK and Akt signaling pathways at least partially though up-regulation of FLT4, COL11A1, and NID1 in lung cancer cells." (PMID 28555007, 2017).